MDM2 (MDM2 proto-oncogene)
Diseases named in the same sentence as MDM2 in open-access papers (continued):
Sharing a sentence is not in itself a finding about the gene and the disease.
cancer (continued). "Elevated levels of MDM2 in tumors are associated with a less favorable outlook for individuals with cancer." (PMID 38601081, 2024). "As seen in several cancers, MDM2 activity is associated with cancer progression and evasion from apoptosis." (PMID 38534381, 2024). "The discovery of the synergistic effect of this combination therapy and the elucidation of the underlying molecular mechanisms indicates that cancers with excessive mitophagy activation are more amenable to treatment with MDM2 inhibitors." (PMID 39215364, 2024). "This is likely due to the presence of BRCA2, PTEN, and MDM2 mutations, which make this type of cancer responsive to platinum-based chemotherapy." (PMID 39201255, 2024). "It is worth noting that overexpressing MDM2 in cancer cells reduces DNA DSBs caused by VP-16 therapy, and MDM2-amplified cancer cells show selective resistance to TOP2 poisons and not to other genotoxic agents." (PMID 38263255, 2024). "Overexpression of MDM2 is associated with poor prognosis and advanced stages of cancer, making it a promising target for the development of anti-cancer therapies." (PMID 37314603, 2023). "Although a correlation between the high expression of MDM2 and immunosuppressive activities of cancer cells has been established, the underlying mechanism is yet to elucidate." (PMID 37314603, 2023). "The association of our target miRNAs with MDM2 has been a significant observation as this gene is found to be dysregulated in several cancers." (PMID 37374977, 2023). "The pathogenic role of MDM2 in initiation, progression, metastasis, and chemotherapy resistance of cancer is majorly attributed to gene mutation and deregulated expression." (PMID 37314603, 2023). "In any case, an abundant level of MDM2 in cancer cells is directly associated with poor clinical prognosis, as well as with weaker responses to routine anticancer treatment." (PMID 36770991, 2023). "The occurrence of splice variants of MDM2 also contributes to the increased aggressiveness of various cancers." (PMID 37314603, 2023).
cancer (continued). "MDM2 overexpression has been implicated in various processes associated with human and mouse malignant tumors, including cell proliferation, DNA damage response, cell cycle regulation, and apoptosis." (PMID 37297833, 2023). "The rationale behind this drug combination stems from the observation that MDM2 amplification is associated with rapid disease progression in patients receiving PD-1/PD-L1 inhibitors in various cancers." (PMID 36923534, 2023). "Amplification and overexpression of the MDM2 gene have been characterized in various cancers, and high MDM2 expression is usually linked with higher patient mortality." (PMID 36609449, 2023). "Overexpressed MDM2 is associated with disease progression and chemotherapy resistance, under influence of which the prognosis of patients with cancers is poor." (PMID 37217945, 2023). "Single nucleotide polymorphisms have been observed in the MDM2 gene, correlating with tumor development and progression and an earlier onset of cancer occurrence." (PMID 36980876, 2023). "In most cancers, higher MDM2 concentrations were associated with a poorer clinical prognosis and a more advanced stage of the disease." (PMID 37185737, 2023). "Molecularly, WD LPS and DD LPS share amplified segments of chromosome region 12q13-15, which contains a number of cancer-related genes implicated in tumorigenesis, including MDM2 and CDK4." (PMID 37760460, 2023). "The MDM2 C305F mutation, which was found in cancer patients, renders MDM2 unable to bind to the 5S RNP." (PMID 37526268, 2023).
cancer (continued). "GSEA analysis revealed that MDM2 overexpression phenotype was associated with enrichment of ten hallmark cancer gene sets." (PMID 35326742, 2022). "Most interestingly, as exemplified with MDM2, multiple cancer checkpoint genes were also linked to either low CNV or low expression, suggesting that the CYCLOPS phenomenon applies to some key cancer checkpoints as well." (PMID 35879727, 2022). "It is inactivated in the majority of human cancers, resulting from mutations or the overexpression of its negative regulators, murine double minute 2 (MDM2) and/or murine double minute X (MDMX)." (PMID 35744849, 2022). "The proto-oncogene MDM2 is frequently amplified in many human cancers and its overexpression is clinically associated with a poor prognosis." (PMID 35625571, 2022). "Our research has also increased the understanding of MDM2’s cancer promoting function, detailing how it can cause its related cell dysfunction by degrading KL." (PMID 35468874, 2022).
cancer (continued). "Hyperprogression occurs in 10–30% of cancers treated with immunotherapy and has been associated with MDM2 amplification." (PMID 33314633, 2021). "More importantly, MDM2 has been shown to be functionally linked with the regulation of cancer metabolism in animal models." (PMID 33805973, 2021). "Combined AKT/mTOR and MDM2 inhibition caused a synergistic antiproliferative effect and accelerated apoptosis in glioblastoma multiforme cells, a cancer type with high resistance to conventional chemotherapy." (PMID 34911439, 2021). "In embryonic stem cells, association of HBO1 and Niam (Nuclear Interactor of ARF and Mdm2) is essential in early development, cell survival, as well as cancer progression." (PMID 33754016, 2021). "Researchers in South Korea led by Sang Yoon Kim and Seong Who Kim at the University of Ulsan, Seoul, investigated the role of the proteins Sirt6, Sirt1 and MDM2 in controlling the death of cancer cells caused by chemicals called reactive oxygen species (ROS)." (PMID 33727672, 2021). "Overexpression of these proteins is oncogenic and a risk for cancer, as relevant to our earlier discussion of SNPs, and MDM2 amplification and their examination in the context of sex is warranted." (PMID 33664771, 2021). "The validity of the new experimental model (cell line) was also supported by the observation that high expression of MDM2 was associated with a poor prognosis for NSCLC cancer patients." (PMID 34572735, 2021).
cancer (continued). "Subsequent studies have shown that MDM2 is overexpressed and amplified in several hematological cancers and solid tumors, and high MDM2 levels are associated with a poor prognosis in patients with cancer." (PMID 32397368, 2020). "Since the identification of increased expression of MDM2 variant in a range of human cancers and decreased expression in normal tissue in 1996, more than 72 kinds of MDM2 splice variants have been observed in both cancer and normal cells." (PMID 32477121, 2020). "Consistently, the MDM2-encoding gene was found to be overexpressed or amplified in various human cancers." (PMID 32660118, 2020). "Post-translationally modified splice variants of MDM2 have also been reported in some cancer cell lines." (PMID 32397368, 2020). "Other studies have indicated an additional potential role in MDM2 expression and cancer risk for an Indel (insertion/deletion) polymorphism located at position -2026_-2025 in the constitutive promoter P1 region of the MDM2 gene." (PMID 33202864, 2020). "MDM2/4 as well as EGFR amplifications are supposed to be associated with hyperprogression on ICI in diverse cancers." (PMID 32110946, 2020).